PIK3CA (phosphatidylinositol-4,5-bisphosphate 3-kinase catalytic subunit alpha)
Diseases named in the same sentence as PIK3CA in open-access papers (continued):
Sharing a sentence is not in itself a finding about the gene and the disease.
vascular malformation (continued). "PIK3CA-related disorders include vascular malformations and overgrowth of various tissues that are caused by postzygotic, somatic variants in the gene encoding phosphatidylinositol-3-kinase (PI3K) catalytic subunit alpha." (PMID 34238334, 2021). "Identification of PIK3CA mutations as drivers of vascular malformations has opened up a possibility for the therapeutic use of PI3K inhibitors in these diseases." (PMID 32513927, 2020). "Activating mutations in the PIK3CA gene have very recently also been found in patients with venous malformations, underlining the need for a causal therapy of vascular malformations, e.g. with kinase inhibitors." (PMID 29985963, 2018). "Mosaic mutations of PIK3CA have been associated with the widest spectrum of phenotypes associated with overgrowth and vascular malformations." (PMID 27631024, 2016). "Somatic GOF PIK3CA point mutations have been frequently described in various cancers as an oncogene, as well as in many forms of vascular anomalies, especially the well-known vascular malformations (VMs)." (PMID 37109059, 2023). "Interestingly, PIK3CA hotspot mutations are also found in a subset of overgrowth disorders which involve vascular malformations and are classified as PROS (PIK3CA-related overgrowth spectrum)." (PMID 32350708, 2020). "Most PROS syndromes are characterized by vascular malformations (VMs), suggesting that PIK3CA somatic mutations could occur in vascular endothelial cells (EC)." (PMID 29352118, 2018). "As seen in human PRD vascular malformations, mosaicism for constitutively active Pik3ca entailed the permanent loss of pericytic coverage, while both endothelial proliferation and pericyte loss could be reversed in this model upon administration of an Akt inhibitor." (PMID 36353506, 2022). "Mutations in PIK3CA, TEK, GNAQ, and GNA11 have been identified in various types of vascular malformations and hemangiomas." (PMID 40428263, 2025). "In clinical trials of sirolimus for vascular malformations, long-term efficacy was reported in 84% and 83% of patients with TIE2 and PIK3CA mutations, respectively." (PMID 40748519, 2025). "PIK3CA inhibitors such as BYL719 are also expected to be effective in particular on vascular malformations of SOLAMEN." (PMID 39080810, 2024). "In conclusion, we have presented a novel mouse model of vascular malformations and provided encouraging preliminary evidence of alpelisib’s efficacy in patients with either PIK3CA or TEK-related capillary venous malformations." (PMID 38880808, 2024). "systematically reviewed 69 studies, finding that mutations in TIE2, PIK3CA, and PIK3R1 primarily manifested as small blue, low‐flow vascular malformations." (PMID 39654683, 2024). "Mammalian target of rapamycin (mTOR) inhibitors, immunosuppressants used in transplant medicine, have been repurposed to target patients with PIK3CA-related vascular malformations and segmental overgrowth." (PMID 34916230, 2023). "To test this, we reduced miransertib dose by half (35 mg/kg) and evaluated its efficacy on preventing Pik3ca‐driven vascular malformations." (PMID 35695059, 2022). "Cell cycle progression in Pik3caH1047R ECs is responsive to growth factors; thus, active angiogenesis is required for the formation of Pik3ca‐driven vascular malformations." (PMID 35695059, 2022). "Next, we analyzed the response of PIK3CA-driven vascular malformations to inhibition of VEGF-C signaling in vivo." (PMID 32513927, 2020). "Ongoing clinical trials assessing the efficacy of Sirolimus (mTOR inhibitor Rapamycin) for the treatment of PIK3CA-driven vascular malformations have shown promising results." (PMID 32513927, 2020). "Activating PIK3CA mutations are also present in syndromes that now fall under the umbrella of PIK3CA-related overgrowth spectrum (PROS), in which vascular malformations are often a key feature." (PMID 29190660, 2017).
vascular malformation (continued). "Several individuals lacked megalencephaly, and had variable somatic overgrowth with vascular malformations, further expanding the spectrum of PIK3CA-related overgrowth." (PMID 27631024, 2016). "Although everolimus showed capacity to treat PIK3CA-mutated mouse model of vascular malformations, no further systematic clinical studies were conducted afterward, except several case reports." (PMID 41430313, 2025). "First, we performed manual analysis and variant calling of the sequencing data for the genes known to cause HHT (ACVRL1, ENG, GDF2, SMAD4) or vascular malformation syndromes with similar phenotypes (EPHB4, RASA1), as well as PIK3CA, which has been shown to modify vascular malformation phenotypes." (PMID 39062925, 2024). "Sporadic venous malformations, the most common type of vascular malformations, are caused by gain‐of‐function mutations either in the endothelial tyrosine kinase receptor TEK/TIE2 or in the PI3K catalytic subunit alpha PIK3CA; with TEK and PIK3CA mutations largely being mutually exclusive." (PMID 35695059, 2022). "Previous preclinical studies of miransertib using tumour xenografts showed that the minimum dose that has an impact on tumour volume is 75 mg/kg; thus, we first evaluated this dose to assess miransertib for preventing the formation of Pik3ca‐driven vascular malformations." (PMID 35695059, 2022). "To further understand whether Pik3ca‐related vascular malformations emerge as a consequence of enhanced EC proliferation, we postulated that the analysis of ECs in S‐phase had to be done before the accumulation of too many ECs." (PMID 35695059, 2022). "This resembles the human spectrum of vascular malformations where PIK3CA mutations have not been reported in arterial malformations." (PMID 35695059, 2022). "Recently, sirolimus, a mammalian target of rapamycin inhibitor, has been increasingly used for complicated vascular malformations, and the targeted PIK3CA inhibitor alpelisib (BYL719) was recently administered with significant clinical benefit in SVMs in the PIK3CA-related overgrowth spectrum." (PMID 34362421, 2021). "And recurrently mutated genes were identified in several vascular malformations as well including TEK/TIE2 mainly in venous malformations, GNA11/14 mainly in vascular tumors, KRAS/NRAS/RASA1/HRAS mainly in AVMs, GNAQ, IDH1/2, AKT1, PTEN and PIK3CA." (PMID 34736485, 2021). "Based on a shared molecular diagnosis, we could speculate that treatment with Alpelisib could be able to induce a reduction and an improvement also in isolated PIK3CA-related vascular malformations, such as venous or lymphatic malformations." (PMID 34568242, 2021). "PIK3CA mutations have also been implicated in non-malignant conditions including congenital overgrowth syndromes and vascular malformations." (PMID 31018529, 2019). "In patients with slow-flow vascular malformations (SFVMs) including venous malformations (VM), lymphatic malformations (LM) or Klippel–Trenaunay Syndrome (KTS), somatic gain-of-function mutations in genes encoding phosphatidyl inositol 3-kinase alpha (PI3Kα, gene name PIK3CA) have been identified." (PMID 39930502, 2025). "Moreover, PIK3CA mutations are responsible for a group of disorders characterized by segmental overgrowth of various tissues with or without vascular malformations, which are also termed as PIK3CA-related overgrowth spectrum (PROS)." (PMID 37658401, 2023). "The somatic mutation spectrum of vascular malformations in Chinese population is similar to that reported in other populations, but non-hotspot PIK3CA mutations may also be prevalent." (PMID 37658401, 2023). "Interestingly, although present from birth, the PIK3CA mutations found in PROS and vascular malformations are similar to those found in solid tumours, with the H1047R mutation being the most common but occur in a mosaic pattern, mainly in tissues of mesodermal origin." (PMID 31018529, 2019).
vascular malformation (continued). "Similarly, somatic/mosaic PIK3CA mutations are found in the majority of LM and complex malformations (KTS), underscoring mTOR activation as an interesting target for medical treatment of slow-flow vascular malformations." (PMID 30373605, 2018). "However, even in the absence of vascular malformations, there is a heightened risk for thrombosis which can be attributed to vascular endothelial dysfunction and particular endothelial adhesion molecules found in individuals with PIK3CA mutation." (PMID 38813336, 2024). "The mTOR inhibitor sirolimus may also be worth studying in view of the established interaction and coregulation of PIK3CA/AKT/mTOR with the MAPK/MEK/Ras pathway, as well as its successful usage in treating complex vascular malformations." (PMID 37106420, 2023). "The identified PIK3CA mutations have been previously reported in other patients with PROS, and the KRAS and TEK mutations in patients with vascular malformation, but the MAP2K3 and TBC1D4 mutations have not been previously reported." (PMID 36175890, 2022). "PROS would then be considered a subcategory of PIK3CA-related disorders along with PIK3CA-related vascular malformations and PIK3CA-related nonvascular lesions." (PMID 34238334, 2021). "Therefore, for the purpose of this review article, it is not possible to pinpoint specific vascular malformations and their response to PIK3CA inhibitors." (PMID 39290395, 2024). "However, many patients with PIK3CA-related vascular malformations or other PIK3CA-related lesions do not present with tissue overgrowth." (PMID 34238334, 2021). "Among non-cancerous disorders, PIK3CA mutations define the PIK3CA-Related Overgrowth Spectrum (PROS), encompassing a wide range of conditions characterized by segmental tissue overgrowth and vascular malformations, including CLOVES syndrome, KTS, CLAPO syndrome, and fibro-adipose vascular anomaly." (PMID 41300578, 2025). "PIK3CA-related disorders include PIK3CA-related overgrowth spectrum (PROS), PIK3CA-related vascular malformations, and PIK3CA-related nonvascular lesions." (PMID 34238334, 2021).
triple-negative breast carcinoma (60 papers, 2010 to 2025). An invasive breast carcinoma which is negative for expression of estrogen receptor (ER), progesterone receptor (PR), and human epidermal growth factor receptor 2 (HER2). "Triple-negative breast cancer (TNBC) constituted 8/61 (13.1%) of PIK3CA-WT tumors and only 2/42 (4.8%) of mutated tumors; however, this difference was not statistically significant." (PMID 37761256, 2023). "The prevalence of PIK3CA mutation was relatively lower in triple-negative breast cancer (27.0%) and premenopausal patients with HR+/HER2– status (29.0%)." (PMID 37655108, 2023). "Among patients with triple-negative breast cancer, evidence from a study with 119 patients seems to suggest a positive prognostic impact of a PIK3CA mutation." (PMID 36131248, 2022). "The aim of this study is to determine if vitamin C, a potent epigenetic regulator, can improve the therapeutic outcome and reduce the dose of buparlisib in treating PIK3CA-mutated triple negative breast cancer (TNBC)." (PMID 33664847, 2021). "INPP4B loss, which occurs most frequently in triple-negative breast cancer where PIK3CA mutations are rare, enhances oncogenic PI3K/AKT signaling." (PMID 34035258, 2021). "A recent study has shown that mutation in PIK3CA corresponds to a poor prognosis in patients with hormone receptor-positive metastatic breast cancer but a good prognosis in patients with triple-negative breast cancer." (PMID 34335799, 2021). "HR, HER2 status, germline BRCA status as well as PIK3CA mutation status in HR-positive and PD-L1 in triple-negative breast cancer (TNBC) should be assessed to allow for targeted therapies." (PMID 33743073, 2021). "Lehmann BD and co-workers detected highly clonal PIK3CA mutations in the triple negative breast cancer subtype that present a luminal phenotype and express androgen receptors (40%) versus triple negative breast cancer without androgen receptors (4%)." (PMID 33375317, 2020). "Nevertheless, half of all the HER2 subtype tumors carried at least one mutation, and PIK3CA mutations were more frequently found in estrogen receptor-positive cancers compared to triple negative breast cancer." (PMID 26968814, 2016). "In the present study, the mutation rate of PIK3CA in triple negative breast cancer was 13% (5/39)." (PMID 30227836, 2018). "For instance, PIK3CA mutations drive migration and EMT transition in triple-negative breast cancer (TNBC)." (PMID 41362647, 2025). "Other studies have shown that luminal A has a prevalence of 49% in PIK3CA mutations, while BRCA1 and BRCA2 mutations are characteristic of triple negative breast cancer." (PMID 39264897, 2024). "The PIK3CA gene is a linchpin in the intricate molecular network governing triple-negative breast cancer (TNBC) tumor tropism, serving as a focal point for understanding this aggressive disease." (PMID 39369580, 2024). "DANCR-induced RXRA phosphorylation suppressed RXRA-inhibited PIK3CA transcription in triple negative breast cancer cells and ultimately activated the downstream PI3K/AKT signaling." (PMID 33123287, 2020).
triple-negative breast carcinoma (continued). "Moreover, gedatolisib and palbociclib also showed additive growth-inhibitory effects in HCC1806, an RB-positive, PIK3CA-amplified, triple negative breast cancer cell line that is relatively resistant to palbociclib." (PMID 40565304, 2025). "Cell viability assays, which were conducted with triple-negative breast cancer (TNBC) cell lines harboring PIK3CA hotspot mutations, demonstrated a significant reduction in the proportion of early cell apoptosis in the PIK3CA mutant group compared to the PIK3CA wild-type group (p = 0.04)." (PMID 40142329, 2025). "Understanding PIK3CA's orchestration of these molecular processes offers insights into the complexities of tumor tropism, paving the way for targeted therapeutic strategies in aggressive cancers like triple-negative breast cancer." (PMID 39369580, 2024). "Substantial statistical heterogeneity among eligible studies (I2 > 50%) was observed in most of the analyses, except for the overall discordance rate of PIK3CA mutational status from mutated to wild-type and the HER2 + and triple-negative breast cancer (TNBC) subgroup analyses." (PMID 37392328, 2023). "According to reports, PIK3CA can serve as unfavorable prognostic biomarkers and could be considered for targeted therapy for triple negative breast cancer (TNBC) patients with a poor prognosis." (PMID 38034788, 2023). "In particular, PIK3CA activating mutations comprise up to 47% of HR+/HER2– (luminal A), 33% of HR+/HER2+ (luminal B), 39% of HR-/HER2+ (HER2-enriched), and 8–25% of basal-like/triple negative breast cancer subtypes." (PMID 34298731, 2021). "PIK3CA and AKT1 mutations were found to be particularly enriched in the luminal B/HER2− subtype, NF1, and ERBB2 mutations were enriched in the luminal B/HER2+ mutation, and PTEN mutations were enriched in triple-negative breast cancer." (PMID 33173047, 2020). "This pathway is frequently activated in triple negative breast cancer (TNBC), via molecular abnormalities such as PIK3CA mutations or loss of PTEN function.As has been observed previously, PIK3CA oncogene mutations were more common in TNBC unlike Akt1 and PTEN mutations." (PMID 30227836, 2018). "From a molecular point of view, mutations in PIK3CA, PIK3R1 and PTEN genes are significantly more frequently found in MBC as compared to triple-negative breast carcinomas of no special type." (PMID 32127014, 2020).